LINC01160 (long independently transcribed non-coding RNA 1160)
Gene: Long non-coding RNA gene on chromosome 1 (111,599,655 to 111,608,723, reverse strand). Ensembl gene ENSG00000231346.
Diseases named in the same sentence as LINC01160 in open-access papers:
LINC01160 is named in the same sentence as 1 disease in open-access papers, as found by Europe PMC text mining. Sharing a sentence is not in itself a finding about the gene and the disease.
LINC01160 shares sentences with these, for which no sentence is quoted: head and neck squamous cell carcinoma (1 paper).